BCL2 (BCL2 apoptosis regulator)
Diseases named in the same sentence as BCL2 in open-access papers (continued):
Sharing a sentence is not in itself a finding about the gene and the disease.
melanoma (continued). "At the same time, downregulation of Bcl-2, Bcl-xL and Mcl-1 by (+)-bornyl p-coumarate may induce autophagy-dependent apoptosis in melanoma cells." (PMID 32466337, 2020). "In support of bcl-2 as cancer-associated orchestrator of TAM recruitment and functions, a massive in vivo recruitment of M2-polarized macrophages was observed both in human and murine melanoma models injected in mice." (PMID 32269145, 2020). "It has been reported that human melanoma cell apoptosis could be induced by negatively regulating the Erk/PKM2/Bcl‐2 axis." (PMID 32248666, 2020). "Higher production of tumor-promoting and chemotactic factors, and M2-polarized activation was observed when macrophages were exposed to culture media from melanoma cells overexpressing bcl-2, while bcl-2 silencing in melanoma cells inhibited the M2 macrophage polarization." (PMID 32269145, 2020). "Conversely, resistance to MEK inhibition in NRAS-mutant melanoma may be mediated through activation of the anti-apoptotic cAMP/MITF/Bcl-2 pathway." (PMID 32517051, 2020). "These sesquiterpene lactones were cytotoxic against human acute myeloid leukemia (U-937 and HL-60) cells, even in cells over-expressing the pro-survival protein Bcl-2, but melanoma (SK-MEL-1) and human mononuclear cells isolated from blood of healthy donors were more resistant." (PMID 32316340, 2020). "Therefore, this study can serve as the starting point for clinical trials that combines MCL1 inhibitors with BCL2 inhibitors for patients with advanced melanoma." (PMID 32764384, 2020). "Thus, our data along with current clinical trials provide the framework for testing the efficacy of the combination of MCL1 inhibitors with BCL2 inhibitors in melanoma patients." (PMID 32764384, 2020). "Sinomenine significantly inhibited caspase-3 activity and the viability of B16-F10 mouse melanoma cells and induced apoptosis and related proteins expression (Bax/Bcl-2 ratio) at 25, 50 and 100 μM in a CCK-8 assay and Annexin V stained cell counting as well as in Western blot analysis." (PMID 32962182, 2020). "In melanoma, hypoxia-induced VE-cadherin expression is regulated by Bcl-2." (PMID 32993787, 2020). "The study of Bcl-2 proteins in melanoma followed the same trend and also focused on BCL2, Bcl-xL, and MCL1 although, to our knowledge, a comprehensive study of the relative expression of all six anti-apoptotic Bcl-2 proteins in melanoma cells or tumors has not been performed yet." (PMID 33396645, 2020). "From in vitro studies, after osthole intervention (20, 40, and 80 mol/L) on melanoma A375 cells, the mRNA level of Bcl-2 declined, same as the expression of p-NF-κB and Bcl-2 protein level in a dose-dependent manner, the mRNA level of Bax and the expression of IκB-α increased." (PMID 32028721, 2020). "Additionally, exogenous ERDR1 treatment decreases cancer cell proliferation and tumor growth in melanoma as a result of increased apoptosis via the regulation of apoptosis-related molecules—Bcl-2 and Bax." (PMID 32283647, 2020). "Furthermore, in melanoma cells, overexpression of bcl-2 correlated with the tumor ability to reprogram macrophage polarization toward M2 through bcl-2-dependent IL-1β production." (PMID 33212945, 2020). "In this study, our findings revealed that the lncRNA LHFPL3-AS1-long, generated from the polypyrimidine tract binding protein 1 (PTBP1)-mediated splicing of the LHFPL3-AS1 precursor, upregulated BCL2 protein to contribute to tumorigenesis of melanoma stem cells." (PMID 33149126, 2020). "In addition, melanoma cells treated with ACF exhibited a significant increase in Bax/Bcl2 ratio, a predictive marker for therapy response." (PMID 33396270, 2020). "Similar to its effects on regular melanoma cells, lj-1-59 treatment causes cell cycle arrest at the G2/M phase and apoptosis, including upregulating the expression of cleaved PARP and BAX and decreasing BCL2 expression." (PMID 32021565, 2020).
melanoma (continued). "Thus the expression levels of VEGF and Bcl-2 genes were characterized in the LHFPL3-AS1-long-silenced melanoma stem cells." (PMID 33149126, 2020). "Importantly, we also observed that melatonin (1 mM) remarkably promoted vemurafenib-induced activation of cleaved caspase-3, cleaved caspase-9 and inactivation of Bcl-2 as well as cleavage of PARP in melanoma cells." (PMID 30717768, 2019). "Different antiapoptotic Bcl-2 proteins may substitute each other, and in melanoma cells the particular roles of Bcl-2, Bcl-xL, and Mcl-1 have been described." (PMID 31083589, 2019). "In the present study, we showed that 1 was able to bind and stabilize G4 structures in vitro that form within the promoters of human KIT, BRAF, and BCL-2, which are three genes that may be relevant therapeutic targets in melanoma." (PMID 31635389, 2019). "Due to the importance of the BCL-2-regulated apoptosis pathway in cancer development and drug resistance, it is of interest to establish which proteins are most important for melanoma cell survival, though the outcomes of previous studies have been conflicting." (PMID 31019203, 2019). "Indeed miR-204-5p enforced expression in M14S melanoma cells reduced Bcl-2 expression levels both at RNA and protein levels." (PMID 30254376, 2019). "Finally, a concomitant decrease in the expression of Sema5A, Bcl-2 and c-Myb proteins was observed in melanoma cells after miR-204 overexpression." (PMID 30454024, 2018). "Melanoma cells underwent DATS-induced apoptosis via downregulation of Bcl-2 and Bcl-xl expression." (PMID 29565284, 2018). "Based on RNA-sequencing analyses of nevi and primary melanoma samples, increased pro-apoptotic BCL-2 family expression positively correlates with high-risk disease suggesting a highly active anti-apoptotic BCL-2 protein repertoire likely contributes to worse outcome." (PMID 29348439, 2018). "Interestingly, we found a higher level of c-Myb at both mRNA and protein levels in Bcl-2 overexpressing melanoma cells, and in accordance with this result, the recruitment of the c-Myb protein at the Sema5A promoter was enhanced by Bcl-2 forced expression." (PMID 30454024, 2018). "Furthermore, the application of BCL-XL/BCL-2 inhibitors induces apoptosis in melanoma cells at different clinical stages including melanoma-initiating cells." (PMID 29238043, 2017). "Our results showed that compound 1 inhibited the level of Bcl-2 in melanoma cells." (PMID 28570563, 2017). "Additionally, chaetocin treatment significantly up-regulated the protein levels of Bax, cleaved caspase-9/-3, simultaneously down-regulated the protein levels of Bcl-2, procaspase-9/-3, and activated caspase-9/-3 activity in the melanoma cells." (PMID 28419143, 2017). "Meanwhile, leflunomide treatment induced cell apoptosis and deficiency of DHODH sensitized cells to drug-induced apoptosis in BCL-2 deficient melanoma cells, while not in BCL-2 abundant melanoma cells." (PMID 29348830, 2017). "The results of flow cytometry also showed that BCL-2 promoted cell cycle arrest in melanoma cells." (PMID 29348830, 2017). "This further supports that an MCL-1/BCL-2 co-targeting strategy could be beneficial for melanoma patients, especially those relapsed from other treatments." (PMID 27086916, 2017). "It was needed to be further determined whether the piceatannol-induced apoptosis of melanoma cells was involved in the expression of pathway regulatory proteins, caspase-3, Bcl-2 and Bax." (PMID 29041990, 2017).
melanoma (continued). "Similarly, we previously showed that under hypoxia BCL-2 promotes HIF-1-mediated VEGF expression in melanoma and breast carcinoma." (PMID 29238043, 2017). "Ab melanoma cells constitutively express survivin, Bcl-2, and Bcl-XL proteins (unpublished data)." (PMID 28281027, 2017). "Besides, BCL-2 was considered as an oncogene in multiple tumors, including melanoma, and contributed to cancer cell survival." (PMID 29348830, 2017). "Furthermore, high expression of Bcl-2 is correlated with resistance to chemotherapy in human melanomas and other tumors." (PMID 26784177, 2016). "Melanoma cell lines were exposed to 100μM propranolol for 24h, Bax was significantly increased in A375 (Aa, P <0.001), P-3 (Ab, P <0.01) and P-6 (Ac, P <0.01) cell lines, while Bcl-2 was decreased in the three melanoma cell lines (Ba-Bc, P <0.01)." (PMID 27582542, 2016). "Thus, we investigated the effect of CoQ0 on the expression of anti-apoptotic Bcl-2 and pro-apoptotic Bax in melanoma cells." (PMID 26968952, 2016). "Our data suggest that VS-5584, or plus Bcl-2/Bcl-xL inhibitors, may be beneficial for patients with melanoma." (PMID 26204252, 2015). "In vitro, DM-1 also induced apoptosis via the extrinsic pathway by TNF-R1 and cleaved caspase-8 increase and by the intrinsic pathway via Bcl-2/Bax ratio decrease, cytochrome-c release and the electric mitochondrial membrane potential decrease in melanoma cells." (PMID 25742310, 2015). "Bcl-xL and Bcl-2 play an important role in melanoma cell resistance." (PMID 26204252, 2015). "There are also evidences that Bcl-2 overexpression may stimulate Sphk1 expression and activity in human melanoma cells." (PMID 25056275, 2015). "Inhibition of Bcl-2/Bcl-xL could further enhance the activity of VS-5584 against melanoma cells in vitro and in vivo." (PMID 26204252, 2015). "Furthermore, melanoma tumors treated with DM-1 showed a preferential apoptotic intrinsic pathway by decreasing Bcl-2/Bax ratio." (PMID 25742310, 2015). "Collectively, these results indicate that inhibition of Bcl-xL/Bcl-2 could significantly sensitize VS-5584’s activity against melanoma cells." (PMID 26204252, 2015). "Neither of the three cytostatic compounds influenced the band pattern of Bcl-2 in either one of the both melanoma cell lines; however, the overall protein expression levels appeared to be slightly higher in the high metastatic B16F10 cell line compared to all samples of the B164A5 cell line." (PMID 25756279, 2015). "Importantly, the Bcl-xL/Bcl-2 inhibitor ABT-737, or siRNA-mediated knockdown of Bcl-xL/Bcl-2, remarkably enhanced the activity of VS-5584 against melanoma cells in vitro and in vivo." (PMID 26204252, 2015). "Co-treatment with BRAF inhibitors and with inhibitors of BCL2 might overcome intrinsic resistance to BRAF inhibitors (also seen in melanoma cells in vitro and in vivo)." (PMID 26636651, 2015). "Indeed, the blockade of BCL2 activity has shown promising results in several cancers, such as pediatric lymphoblastic leukemia, neuroblastoma, melanoma, genitourinary neoplasm, and glioblastoma." (PMID 25762636, 2015). "Besides, previous studies have shown reduced expression of Bcl-2 in melanoma as compared to melanocytes and benign nevi, ruling out the involvement of Bcl-2 in our study." (PMID 26497853, 2015). "A375 is a human-derived melanoma cell line harboring a BRAF mutation due to the substitution of valine for glutamic acid at codon 600, termed V600E resulting in constitutive activation, aggressive proliferation, and high BCL-2 expression." (PMID 24832107, 2014).
melanoma (continued). "Interestingly, the knockdown of CRAF in melanoma cells with non V600E mutations in BRAF induced apoptosis through a reduction in BAD phosphorylation and Bcl-2 expression." (PMID 25422890, 2014). "Interestingly, MITF is an oncogene in melanoma, and leads to cell survival via upregulation of BCL2 and other molecules." (PMID 24827933, 2014). "Furthermore, the association of selumetinib with ABT-263, a BH3-mimetic that disrupts the interactions of Bcl-2 and Bcl-XL with pro-apoptotic proteins, also induced caspase-dependent cell death in A375 melanoma cell line." (PMID 24920406, 2014). "In this study, we found that anti-cancer activity of CACF may be attributed to Bcl-2 downregulation in melanoma cells." (PMID 23837445, 2013). "Taken together, these results suggest that targeting of Mcl-1 by Maritoclax may represent a new therapeutic strategy for melanoma treatment that warrants further investigation as a single therapy or in combination with other agents such as Bcl-2 inhibitors." (PMID 24223823, 2013). "Therefore, the reduced expression of Bcl-2 and cIAP (an inhibitor of caspase 3) after treatment of melanoma cells with iRF is indicative of apoptosis induction." (PMID 23342114, 2013). "Thus, Bcl-2 downregulation by CACF is an effective way in sensitizing human melanoma cells to apoptosis." (PMID 23837445, 2013). "Several randomized, controlled, phase III trials have evaluated the utility of antisense Bcl-2 combined with standard chemotherapy for the treatment of patients with chronic lymphocytic leukemia, multiple myeloma, malignant melanoma, or non-small cell lung carcinoma." (PMID 23229564, 2013). "In addition, antiapoptotic Bcl-2 proteins like Bcl-2, Bcl-w, or A1, which were strongly expressed in melanocytes, were only expressed at low levels in some melanoma cell lines, such as WM3211, WM1158, and WM1232." (PMID 22292048, 2012). "We found that melanoma cells required the presence of specific antiapoptotic Bcl-2 proteins: Inhibition of Mcl-1 and A1 strongly induced cell death in some melanoma cell lines, whereas non-malignant cells, i.e., primary human fibroblasts or keratinocytes were not affected." (PMID 22292048, 2012). "Interestingly, this includes many genes that we found commonly regulated between fish and human melanoma (e.g. BCL2, WNT family members) or which became evident in the fish tumor comparisons, e.g. components of the ECM, cell cycle regulators, PLP1, and CLIC3." (PMID 22693581, 2012). "However, all melanoma cell lines tested in our study were sensitive to at least one of both Bcl-2 members." (PMID 22292048, 2012). "BCL-2 is overexpressed in melanoma: Factors including NRas and MITF may also contribute to increased Bcl-2 activity." (PMID 21479172, 2011). "In this study we evaluated whether electroporation could increase the delivery of antisense oligodeoxynucleotides against bcl-2 (G3139) as well as the efficacy of combination chemotherapy in human melanoma xenografts." (PMID 21798045, 2011). "Bcl-2 overexpression reduced apoptosis and sensitivity of melanoma cells to pro-apoptotic stimuli." (PMID 21479172, 2011). "Harmine could enhance the activation of Bcl-2 family pro-apoptotic proteins such as Bax and Bid while it could also down-regulate the expressions of Bcl-2 in B16F-10 melanoma cells." (PMID 21429205, 2011). "Overexpression of Bcl-2 contributes to metastasis in melanoma." (PMID 24281076, 2010). "Bcl-2 and Bcl-xL are both known to be upregulated in melanoma." (PMID 19684859, 2009).
melanoma (continued). "Statistical evaluation of the results concerning the effects of ABCA1 on response to Curcumin revealed that knocking-down the multidrug resistance gene alone already inhibits expression of the NFκB subunit p65 and the survival factors bcl2 and survivin and induces apoptosis in melanoma cells." (PMID 20030852, 2009). "Thus, taurolidine-induced apoptosis in melanomas correlated with enhanced Bax and reduced Bcl-2 expression, and bortezomib induced expression of Noxa." (PMID 19506730, 2008). "Due to high expression of several antiapoptotic Bcl-2 proteins in melanoma, a simultaneous targeting may be necessary, which may however be difficult to realize in the clinic." (PMID 19506730, 2008). "Also a prognostic value of proapoptotic Bcl-2 proteins was found, namely down-regulated Bax and Bak in primary melanomas correlated with unfavorable prognosis." (PMID 19506730, 2008). "Approaches directly targeting Bcl-2 proteins in melanoma appear of particular interest." (PMID 19506730, 2008). "In melanoma, the mitochondrial apoptosis pathways and Bcl-2 proteins appear of particular importance for apoptosis resistance, which has been addressed in clinical trials applying antisense-Bcl-2." (PMID 19506730, 2008). "In addition, a CTL antimelanoma clone specific for Melan-A/MART-1 revealed significantly more killing of Bcl-2-overexpressing A02 melanoma cells in the presence of the potent Bcl-2 inhibitor ABT-737." (PMID 17311012, 2007). "Similarly, methylated AS Bcl-2, with 5'-methylation of CpG motif cytosine residues, had the same antitumor effect as unmethylated AS Bcl-2 ODNs in human melanoma xenografts transplanted into mice with severe combined immunodeficiency." (PMID 16280040, 2005). "However, the implication of Bcl-2 antiapoptotic proteins as melanoma progression factors is controversial." (PMID 15305193, 2004). "As an indirect line of support for this concern, thrombocytopenia as dose-limiting toxicity as well as transient leucopenia have been observed in the first clinical trial combining a mild myelosuppressive standard chemotherapeutic regimen with Bcl-2 AS oligonucleotides in melanoma." (PMID 14520471, 2003). "In addition to the previous evidence of a crosstalk between melanoma cells expressing Bcl-2 and component of the TME, such as macrophages and endothelial cells, these results demonstrated a further relationship between melanoma specific Bcl-2 and TME through the activation of fibroblasts." (PMID 38755629, 2024). "Also, TEAD4 transcript level was found decreased after Bcl-2 depletion in melanoma." (PMID 38755629, 2024). "Interestingly, Bcl-2 silencing abrogated the ability of A375 cells to growth in 50 kPa stiffness condition, suggesting a role played by Bcl-2 in regulating the mechanobiology of melanoma cells in response to different tumor environmental properties." (PMID 38755629, 2024). "Hence, we measured the expression of these apoptosis‐related proteins by western blotting, which showed that the levels of cleaved PARP, and cleaved Caspase‐9 were significantly increased and the level of BCL2 was greatly decreased in TRAF6‐knockdown melanoma cells." (PMID 37484971, 2023). "Furthermore, both pro-apoptotic protein proteins (Cleaved caspase 9, Cleaved PARP, Bax) and mRNA (Caspase 9, Bax) levels were significantly increased in a dose-dependent manner in melanoma cells, whereas anti-apoptotic protein and mRNA level of Bcl2 was decreased sharply." (PMID 36339598, 2022). "Also, combining immunotherapy with agents that target the BCL2 antiapoptotic proteins may lead to a more effective treatment in melanoma." (PMID 36325671, 2022). "In addition, lncRNA-XIST promotes the proliferation and migration of melanoma cells by decreasing the expression of PI3KRI and AKT and increasing the expression of Bcl-2 and Bax, which are considered key regulators of oxaliplatin resistance in melanoma progression." (PMID 36601121, 2022).